CSF1R (colony stimulating factor 1 receptor)
Diseases named in the same sentence as CSF1R in open-access papers (continued):
Sharing a sentence is not in itself a finding about the gene and the disease.
tumor (continued). "CSF-1R- OLFM4hi MO-MDSCs are predominantly localized in peripheral tissues such as blood and bone marrow, whereas they are less abundant in the tumor mass." (PMID 39457693, 2024). "CSF-1R plays a role in promoting tumor immune evasion and therapy resistance by stimulating the proliferation, survival, and differentiation of tumor-associated macrophages." (PMID 38791529, 2024). "Recent research demonstrated that CSF-1R signaling enhances cell transformation by supporting tumor cell proliferation, invasion, stemness and drug resistance." (PMID 38254773, 2024). "Emactuzumab (RG7155) is a mAb to CSF-1R that enhances T cell-mediated anti-tumor immune responses via a mechanism of specific inhibition of CSF-1R dimerization and consequent clearance of M2 macrophages expressing the CD163 antigen and CSF-1R." (PMID 39169402, 2024). "The development of more sensitive approaches including RNAscope or new specific anti-CSF-1R antibodies should be investigated in tumor tissue." (PMID 39457693, 2024). "CSF1R regulates macrophage activation, proliferation, and phagocytosis mainly in the tumor immune microenvironment." (PMID 39075190, 2024). "Little is known, however, about the importance of CSF1R expression in tumor cells with an epithelial background." (PMID 38725047, 2024). "The other CSF-1R inhibitor PLX3397 combined with RT decreased tumour size by 100-fold and improved median survival compared to RT alone." (PMID 37686652, 2023). "The CSF-1/CSF-1R signaling pathway is also a primary target for inhibiting MDSC recruitment to tumor sites to constrain tumor progression." (PMID 37415162, 2023). "On the other hand, CSF‐1R, which is secreted by cancer cells into the tumor environment as a strategy to evade the immune system, promotes the growth and recruitment of immunosuppressive myeloid cells." (PMID 38077251, 2023). "Researchers used anti-IL-6 antibody and CSF-1R inhibitors to block the monocytes recruitment into tumor tissue; others by decreasing the population of TAMs, such as anti-CD11b antibody." (PMID 36969873, 2023). "The immune microenvironment was characterized by moderate infiltration of M2-like tumor-associated macrophages (TMAs) with positivity of CD163, CSF1R, CD85A (LILRB3), and PD-L1; moderate PD-1 positive T cells, and low FOXP3 regulatory T lymphocytes (Tregs)." (PMID 36975733, 2023). "In fact, Maf controls the expression of Csf1r in mouse macrophages, where it serves as a switch for the generation of tumor growth-promoting macrophages." (PMID 36380627, 2023). "Enhanced IFN-I signaling and blocked USP18 expression prompt downregulation of colony stimulating factor 1 receptor (CSF1R) and polarization of tumor-associated macrophages toward pro-inflammatory phenotypes." (PMID 38100351, 2023). "We found that administration of anti-mouse CSF1R depleted macrophages from the treated mice and suppressed tumor growth in mice implanted with NB9464 tumors." (PMID 37350973, 2023). "MDSCs express CSF-1 receptors (CSF-1R; CD115) are actively polarized and recruited to the tumor microenvironment." (PMID 37886177, 2023). "Using BLZ945(CSF-1R inhibitor) in a mouse glioma model reduces tumor growth and increases the number of days mice live." (PMID 37138860, 2023). "CSF-1 activation in dt-TGCT leads to recruitment of CSF-1R+ macrophages which make up a large bulk of the tumor mass." (PMID 37114134, 2023). "Because IRAK3 deletion was in the germline in our model, we tested the lineage-specific effects on tumor growth using a myeloid cell depletion antibody against murine CSF-1R." (PMID 36757800, 2023). "In many tumors, CSF1 and its receptor CSF-1R are highly expressed, and inhibition of migration and infiltration of tumor tissue can be observed after inhibiting CSF1." (PMID 37773794, 2023).
tumor (continued). "CSF plays a paramount role in TAM recruitment and survival, and therefore, blockading of the CSF1/CSF1R axis can reduce monocyte recruitment to the tumor site and its differentiation while further hampering the survivability of the existing TAMs." (PMID 38035101, 2023). "Wherein, in BLCA tumor, CSF1R (rho = 0.706), HAVCR2 (rho = 0.686), IL-10 (rho = 0.682), and PDCD1LG2 (rho = 0.753) showed the strongest positive correlation with FAP expression." (PMID 37166418, 2023). "Using a genetic mouse model, the CSF-1R inhibitor BLZ945 caused an acquired resistance via increased macrophage-derived insulin-like growth factor-1 (IGF-1) and tumour cell IGF-1 receptors, ultimately enhancing the PI3K pathway." (PMID 37686652, 2023). "REGO also destroys tumor immunity and survival by inhibiting the colony-stimulating factor 1 receptor (CSF-1R), which is important for macrophage differentiation, and leads to a decrease of tumor-infiltrating macrophages." (PMID 36720853, 2023). "Blockade of M-CSF signaling using anti-CSF1R antibodies severely diminished the number of proliferating KCs in tumor-adjacent areas, leading to impaired expansion of resident KCs upon E. coli–sgMafb/Maf treatment." (PMID 36821387, 2023). "In the same context, several recent studies have shown that the blockage of CSF-1R increases the antitumor response to anti-PD-1 therapy in a wide range of tumor types including ovarian cancer." (PMID 36798830, 2023). "In melanoma, the ERK pathway-mediated RUNX1 transcription factor promotes CSF-1R expression, increasing tumor cell survival and malignancy." (PMID 37153567, 2023). "Further studies are needed to validate the chemokine composition within the tumor microenvironment following combination therapy of CSF1R targeting agents and cancer vaccines." (PMID 37505292, 2023). "Combining CSF-1R inhibition with anti-PD-1/PD-L1 immune checkpoint blockade in TH-MYCN mice enhanced activation of tumor-reactive T cells." (PMID 38087370, 2023). "The possible reason is that after drug treatment, the phenotype of macrophages in the tumor showed obvious M1 switch, and CSF1R was more highly expressed in M2-like macrophages." (PMID 36969873, 2023). "Other strategies targeting the CSF1/CSFR1 axis like CSF1R blockade by PLX3397, an inhibitor for CSF1R tyrosine kinase, have shown to inhibit tumour progression in mouse models of HCC by shifting the polarization of TAMs." (PMID 37894344, 2023). "targeted monocyte and macrophage tumor infiltration with CSF1R and CCR2 inhibitors in a PDAC mouse model." (PMID 37575220, 2023). "Given the importance of CSF1 in macrophage recruitment to the TME, MYCN-amplified PDX-COJEC was xenografted to a nude mouse model to test the effect of anti-CSF1R treatment on inhibiting macrophage recruitment to NB tumours." (PMID 37887559, 2023). "The level of CSF1R on the surface of T cells in the tumor was analyzed and shown to be low, so the possibility of CSF1R acting directly on T cells was less likely." (PMID 36969873, 2023). "The cumulative unbound drug concentration of REG, M-2, M-4, and M-5 estimated from their maximal tumor concentrations is well above the in vitro IC50 both in plasma and in tumor tissue, which should enable CSF1R inhibition in vivo." (PMID 37013652, 2023). "Tumour relapse was allowed to occur by ceasing treatment for three weeks, after which anti-CSF1R treatment was initiated, which led to reduced tumour relapse and growth." (PMID 37887559, 2023). "The administration of CSF1/CSF-1R inhibitors to blockage MDSCs was an effective monotherapy for tumor control and adjuvant therapy to overcome treatment resistance." (PMID 37886177, 2023). "This study contributes to a better understanding of CSF1R kinase aberrancy in cancer, the promising potential in targeting it, and subsequently reprogramming TAMs to disrupt the tumour microenvironment." (PMID 37711590, 2023).
tumor (continued). "For example, several preclinical studies have shown that CSF1R inhibition reduced the tumor growth rate and TAM density, as well as increased sensitivity to chemotherapy." (PMID 38022518, 2023). "Prior research focusing on the targeting of the CSF1/CSF1R signaling axis had shown varied results, from promising data in preclinical models to limited anti-tumor effects later in clinical trials." (PMID 37505292, 2023). "In recent years, several preclinical and clinical trials have explored the combination of CSF1/CSF1R inhibitors with various immunotherapies, such as immune checkpoint blockade, chemotherapy, and radiotherapy in several tumor models." (PMID 37505292, 2023). "This study demonstrates CSF1/CSF1R signaling inhibition enhances the expansion of neoepitope-specific T cells and promotes an immune-permissive tumor microenvironment." (PMID 37505292, 2023). "CSF-1 is another cytokine that allows the recruitment of TAMs to the tumor and several therapeutic strategies aiming at blocking the activation of the CSF-1/CSF1R pathway are currently investigated." (PMID 37143666, 2023). "In response to IL4, TAMs acquire the ability to upregulate expression of insulin-like growth factor 1 (IGF-1), which triggers the signaling of IGF-1R and PI3K, rendering the tumor resistant to CSF-1R inhibition." (PMID 37275361, 2023). "The macrophage colony-stimulating factor (MCSF) cytokines are produced by tumor cells with the function to recruit and polarize TAMs into M2 phenotype by binding with colony-stimulating factor 1 receptor (CSF1R)." (PMID 37705962, 2023). "To conclude, our findings highlight the therapeutic potential of combining CSF1/CSF1R pathway targeting agents with neoepitope targeting vaccines to further modulate anti-tumor immune responses in the tumor microenvironment." (PMID 37505292, 2023). "To further investigate the role of TAMs in vivo, we treated large PE tumor-bearing FVB mice with an anti-CSF1-R antibody to deplete TAMs." (PMID 36817465, 2023). "There has been evidence that tumor recurrence after CSF-1R blockade therapy is common (>50% within a mice model), characterized by a resensitization to CSF-1R inhibition in rGBM." (PMID 37275361, 2023). "For other tumor entities it was shown that TAM depletion by blocking colony-stimulating factor 1 receptor (CSF1R) promoted an anti-tumor immune response and lead to an enhanced response to anti PD-L1 treatment." (PMID 36793050, 2023). "Simultaneously, the inhibition of CSF1R can impact the activity and quantity of macrophages, especially those with immunosuppressive functions in the tumor microenvironment." (PMID 37808190, 2023). "In line with previous studies, we also demonstrated that targeting TAMs in the metastatic tumor microenvironment using an anti-CSF1R antibody augmented the efficacy of anti-PD-1 therapy in liver metastasis." (PMID 37872170, 2023). "In conjunction with paclitaxel, blocking macrophage recruitment with CSF1R-signaling antagonists increased the longevity of mice with mammary tumors by decreasing primary tumor development and lowering pulmonary metastasis." (PMID 37426676, 2023). "Targeting CSF1R in combination with ALOX5 inhibitor effectively reduced tumor volume and M2 macrophage infiltration abundance." (PMID 38124204, 2023). "It has been reported that small molecule inhibitors can restore the antitumor function of T cells and inhibit tumor growth by eliminating CSF1R+ TAM." (PMID 36969873, 2023). "Overall, we demonstrated that CSF1/CSF1R signaling inhibition promotes an immune-permissive tumor microenvironment and enhances neoepitope spreading, resulting in enhanced tumor control." (PMID 37505292, 2023). "Inhibitors blocking the interaction between CSF1/CSF1R reverses the immunosuppressive tumor microenvironment." (PMID 37092846, 2023). "CSF-1R inhibitors can quickly deplete macrophages in tumors and reconstruct tumor microenvironments." (PMID 37124547, 2023).
tumor (continued). "Neutralization of CSF1R or CSF1 has been shown to inhibit tumor growth in a variety of tumor types by inhibiting the proliferation of intratumor macrophages." (PMID 36969873, 2023). "Targeting both CCL2/CCR2 and CSF-1/CSF-1R axis is therefore relevant to a tumor that overexpresses M-CSF, CCL2 and other chemokines that bind to CCR2 such as CCL7." (PMID 38076998, 2023). "Cytokine analysis of tumor spheroid culture media also showed that treatment with anti-CSF-1R Ab or CSF1R/CCR2/TGF-β Ab resulted in reduced release of monocyte chemoattractant proteins CCL2 and CCL7 by 231 TFM spheroids." (PMID 38076998, 2023). "Anti-CD40 mAbs promote TAM transformation to the antitumor phenotype, and synergistic treatment with anti-CSF-1R antibodies stimulates the antitumor activities of TAMs and assists tumor remission." (PMID 37415162, 2023). "CSF1R inhibition reduced the tumor growth rate and TAM density, as well as increased sensitivity to chemotherapy." (PMID 38022518, 2023). "Given pro-tumour functions of TAMs, several CSF1R antagonists have been tested as monotherapy or in combination with ICIs in some malignant tumours." (PMID 37313600, 2023). "Systemic administration of PLX3397, a CSF1R inhibitor, significantly suppressed the primary tumor growth and lung metastasis." (PMID 36814925, 2023). "Together, our data demonstrate that suppression of USP18 promotes UBCH5 and NEDD4-mediated proteasome degradation of CSF1R, leading to an increase in anti-tumor macrophages in the TME." (PMID 38100351, 2023). "TAS-115 is an oral multikinase inhibitor targeting the MET proto-oncogene, VEGFR, and colony-stimulating factor 1 receptor, which helps to inhibit the tumor growth and the osteoclast differentiation." (PMID 37377920, 2023). "CSF-1R inhibitor BLZ945 effectively blocked CSF-1R-expressing suppressive myeloid cell generation and reversed tumor-educated monocyte suppression." (PMID 38087370, 2023). "Pexidartinib, an orally administered tyrosine kinase inhibitor with potent and selective activity against CSF-1R and the capability of modulating tumor microenvironment, has been approved by FDA for patients with giant cell tumors." (PMID 37886177, 2023). "Blocking CSF1R signaling decreases the recruitment of TAMs and reduces tumor growth in several tumor models by elimination or repolarization of TAMs." (PMID 37964379, 2023). "The blocking of the CSF1/CSF1R axis by targeting CSF1 or CSF1R is in clinical trials to eliminate the tumor-promoting macrophage population." (PMID 37279073, 2023). "Under CSF-1R inhibition, the tumor microenvironment drives treatment resistance via stimulation of the PI3K signaling caused by tumor cell IGF-1 receptor (IGF-1R) and macrophage-derived insulin-like growth factor-1 (IGF-1)." (PMID 37012233, 2023). "CSF1R blockade delays tumour growth by shifting the polarization of TAMs toward an M1-like phenotype." (PMID 37894344, 2023). "CSF2 has been shown to mediate resistance to Csf1r inhibition, and to induce accumulation of tumor-promoting myeloid cells." (PMID 37005447, 2023). "In another example, CCL8 produced by TAMs also upregulate tumor cell secretion of colony stimulating factor 1 (CSF-1) which is crucial to macrophage and DC survival and differentiation through signaling via CSF-1R." (PMID 37114134, 2023). "The binding of CSF1 to its receptor, namely colony stimulating factor 1 receptor (CSF1R), promotes the survival and differentiation of human monocytes into macrophages, increased infiltration of TAMs, tumor invasion, metastasis, and angiogenesis." (PMID 37313405, 2023). "For example, previous studies highlighted the potential benefits of combining CSF1R inhibitors with immune checkpoint blockade preclinically; however, most clinical trials testing this combination have yielded insufficient anti-tumor efficacy." (PMID 37505292, 2023).
tumor (continued). "This specific tumor type is well-suited for targeting by CSF-1/CSF-1R pathway blockade; and treatment with anti-CSF-1R antibodies has shown significant reduction of CSF-1R+ TAMs within tumor tissues." (PMID 37114134, 2023). "So, before targeting the macrophage or CSF1/CSF1R pathway, one must consider the tumor subtype and its genetic drivers." (PMID 37279073, 2023). "Results from clinical trials indicate that the anti-tumor effect of CSF-1R inhibitors is still modest, despite their efficacy in targeted M2-TAM treatment." (PMID 37138860, 2023). "Peripheral blood and tumor tissue were analyzed mechanistically by flow cytometry using antibodies against CD115/CSF1R and F4/80 and by ELISA for chemokine (C–C motif) ligand 2 (CCL2) levels." (PMID 37013652, 2023). "CSF1/CSF1R signaling axis had been proved induced macrophages to M2 polarization and promoted tumor growth and lung metastasis." (PMID 37065499, 2023). "This hydrogel gradually released PLX at the tumor site to block colony-stimulating factor 1 receptor (CSF1R) and reduce TAM density." (PMID 37654704, 2023). "Expression of PD-L1, CSF1R, and metabolic enzymes in immunosuppressive CD11c+ cells of tumor-bearing mice and cancer patients." (PMID 35917184, 2022). "CSF1‐secreting malignant T cells can bind to CSF1R to induce the development and survival of TAMs, promoting tumor survival and suppressing host antitumor immunity." (PMID 35441741, 2022). "Similar to the combination treatment of CGP57380 and an anti–PD-1 antibody, the combination of CGP57380 and anti–CSF-1R antibody significantly prolonged the overall survival of tumor-bearing mice." (PMID 35380995, 2022). "Instead, CSF-1R is strongly distributed in TAMs and CSF-1Rhigh TAMs represent a vital cell population in driving tumor immune tolerance." (PMID 35444953, 2022). "Mechanistically, an early response to trametinib treatment sensitized tumors to αPD-1-supplementation by attenuating the expression of tumor-derived CSF-1, which reduced the abundance of two CSF-1R+CD11c+ MDSC populations in the TME." (PMID 35292516, 2022). "Targeting CSF1R signaling in tumor-promoting TAM represents considered an attractive strategy to eliminate or repolarize macrophages cells." (PMID 35346107, 2022). "In contrast, CCL18+ macrophages showed a dominant M2-like phenotype with the high expression of CD163, MARCO, and CSF1R, suggesting their stronger tumor-promoting role than SPP1+ macrophages." (PMID 35347134, 2022). "Our main findings are the following: a) CSF1R+ macrophages promote pleural fluid accumulation by enhancing vascular permeability, destabilizing tumor vessels, and favoring immune suppression." (PMID 35315360, 2022). "Targeting the CSF1/CSF1R axis either alone or in combination with checkpoint blockade, or adoptive T cell therapy has decreased tumor MDSCs and improved anti-tumor responses in multiple tumors." (PMID 35122833, 2022). "In the spleen, intracellular CSF-1R expression in total monocytes remained similar through all cohorts and tumor growth." (PMID 35821822, 2022). "CSF1/CSF1R signaling regulates the number and the function of TAMs, and their activities depend on tumor-type/tissue-specific factors." (PMID 35493517, 2022). "CSF-1R inhibition both restored this balance and increased iNOS+ M1-like macrophages, which produce toxic nitric oxide that lyses tumor cells and promotes phagocytosis." (PMID 36428642, 2022). "Myeloid-cells tumor homing is largely regulated by multiple ligand-receptor interactions, mainly the colony-stimulating factor-1 (CSF1R), the C-X-C Motif Chemokine Receptor 2 (CXCR2), the C-C chemokine receptor type 2 (CCR2) and type 5 (CCR5)." (PMID 36077813, 2022). "We also examined levels of CSF-1R expression in monocytes and macrophages from the bone marrow and splenic compartments in tumor-bearing mice." (PMID 35821822, 2022).